IL6 (interleukin 6)
Diseases named in the same sentence as IL6 in open-access papers (continued):
Sharing a sentence is not in itself a finding about the gene and the disease.
Arthritis (continued). "Moreover, magnolol was able to reverse the IL-1β-induced increase in the expression of genes related to inflammation [IL-6, cyclooxygenase-2 (COX-2), matrix metalloproteinases (MMPs), etc.] in a rat arthritis model by blocking the AP1 signaling pathway, thereby alleviating arthritis." (PMID 39491001, 2024). "Therefore, although tea and tea polyphenols can neutralize the inflammatory effects of IL-1β and IL-6, they also effectively utilize TNF-α to play its basic function of regulating the uncontrolled proliferation of activated synovial fibroblasts to improve the functional status of arthritis joints." (PMID 37033930, 2023). "Finally, local administration of uridine in the joint could prevent the development of antigen-induced arthritis, probably through downregulation of adhesion molecule expression, decreased production of TNF-α and IL-6, and inhibition of leukocyte extravasation." (PMID 36235070, 2022). "In contrast to RA, contribution of the IL-6 priming phase of arthritis may not be important in PsA." (PMID 23133751, 2012). "However, there is no clear scenario of balance between IL-6 and TNFα in arthritis." (PMID 19660107, 2009). "This research described the antioxidant (SOD3, CAT, GPX, ATOX1 and COX18) and immunological (IL-1α, IL-1β, IL-6, IL-10, TNFα, NCF4, NFKB, TMED, FCAMR and iNOS) genes in rams that had arthritis and those that did not." (PMID 40005882, 2025). "Thus, our findings indicate that the neutralization of Gal-9 does not robustly affect the production of MCP-1 and IL-6 in a lymphocyte and monocyte-dominated environment without FLSs, even though galectins are known to be involved in a variety of immune cell modulations in arthritis." (PMID 36672263, 2023). "Of note, serum concentrations of IL-6 and IL-17A were higher in the combined ICI arthritis group than in the PD-1 inhibitor arthritis group, but the differences were not statistically significant." (PMID 35413951, 2022). "Classically, IL-6/gp130/STAT3 signaling has been viewed as a negative regulator of chondrocyte biology and function and is broadly discussed in the context of arthritis and other inflammatory diseases." (PMID 35039652, 2022). "Mediators for inflammation, except TNFα and IL-1, were increased in synovial washouts during SCW arthritis, but none of the inflammatory mediators (KC, MCP-1, IL-6) were significantly different between WT and S100a9−/−." (PMID 32854769, 2020). "In this CAIA model, like in the CIA model, the expression of IL-6 was reduced, but it is important to note that in the CAIA mouse model, IL-6 is not responsible for the progression of arthritis." (PMID 29594389, 2018). "In the murine glucose-6-phosphate isomerase-induced arthritis model, for example, treatment with MTX does not result in decreases in either IL-6 or TNF alpha." (PMID 24444433, 2014). "We have also reported that Kampo therapy resulted in a decrease in serum IL-6 levels, but not TNF-α levels, as well as the suppression of arthritis development, based on the observations of the CIA mouse model." (PMID 22577464, 2012). "In our previous study using CIA, Kampo medicine decreased the serum IL-6 levels, but not TNF-α, suggesting that the suppression of Th17 cell activation by Kampo therapy probably improved the development of arthritis." (PMID 22577464, 2012). "TNF blockade may be used in arthritis-predominant AOSD patients without systemic symptoms and upon suboptimal response to both IL-1 and IL-6 blockade." (PMID 37669122, 2024). "The median IL-6 serum concentrations were raised at the arthritis induction in both diet groups, but the VEGF serum concentrations were in the same range in both diet groups, irrespective of arthritis induction." (PMID 39513899, 2024). "As might be expected, key pro-inflammatory cytokine USRs such as TNF, IFNG, IL6, and IL1B that were upregulated during CHIKV arthritis were downregulated (negative z-scores) in the ameliorated foot swelling seen in Gzma-/- mice." (PMID 35119362, 2022).
Arthritis (continued). "In CIA mice, alantolactone at 50 mg/kg attenuated RA symptoms, including high arthritis scores, infiltrating inflammatory cells, synovial hyperplasia, bone erosion and levels of the proinflammatory cytokines TNF-α, IL-6 and IL-17A, but not IL-10 in paw tissues." (PMID 33556301, 2021). "This implies that IL-6 and TNF-α may not be as important in lung inflammation as it is in arthritis." (PMID 30013577, 2018). "Compared to SNS-gp130flox/flox mice SNS-gp130−/− mice showed significantly weaker initial swelling, reduced serum concentrations of CGRP, IL-6, and IL-2, no inflammation-evoked upregulation of CGRP in sensory neurons, but similar histopathological arthritis scores during AIA." (PMID 26590032, 2015).
metabolic syndrome (849 papers, 2006 to 2026). A cluster of metabolic risk factors for CARDIOVASCULAR DISEASES and TYPE 2 DIABETES MELLITUS. "The associations of dyslipidemia with IL-6 and adiponectin remained significant after adjustment in both sexes." (PMID 39936780, 2025). "Increased levels of IL‐6 are associated with a more severe metabolic syndrome, as assessed by hypertriglyceridemia, hypertension, and elevated fasting glucose levels." (PMID 40630018, 2025). "Conversely, previous studies found that vitamin B12 deficiency is positively associated with inflammatory factors [such as C-reactive protein (CRP) and interleukin 6 (IL-6)], and leads to metabolic syndrome onset and an increase in cardiovascular risk factors." (PMID 40791230, 2025). "This study aimed to examine the associations between inflammatory markers (interleukin-6, tumor necrosis factor-alpha, high-sensitivity C-reactive protein) and metabolic syndrome, with markers of ovarian aging and cardiovascular risk." (PMID 40713717, 2025). "At the same time, dyslipidemia is associated with systemic inflammation, characterized by elevated levels of cytokines such as interleukin-6 (IL-6) and tumor necrosis factor-alpha (TNF-α)." (PMID 39891044, 2025). "Polyphenols also exhibit anti-inflammatory properties, targeting key mediators like nuclear factor-kappa B (NF-κB) and interleukin-6 (IL-6), thereby attenuating chronic low-grade inflammation, often associated with metabolic syndrome." (PMID 38671877, 2024). "Again, BJ was shown to alleviate hepatic steatosis in an animal model of diet-induced metabolic syndrome and cardiovascular risk via the reduction in IL-6 and TNF-α plasma levels and ROS generation." (PMID 38257152, 2024). "C-reactive protein, identified as an acute-phase reactant linked to metabolic syndrome and cardiovascular disease, experiences elevated levels in circulation when interleukin-6 (IL-6) is released by macrophages and T cells." (PMID 38785539, 2024). "This discrepancy suggests the presence of other influencing factors beyond the IL-6 174G > C gene polymorphism in patients with inflammatory diseases like metabolic syndrome or asthma." (PMID 38388670, 2024). "Stress and fatigue have also been associated with elevated levels of monocyte chemoattractant protein and inflammatory cytokines, including IL-1 beta and IL-6, thereby causing high blood pressure and dyslipidemia." (PMID 38398871, 2024). "A high serum level of IL-6 has been linked with dyslipidemia, as shown in patients with oral lichen planus (OLP), a chronic inflammatory disease affecting the mucus membrane of the oral cavity." (PMID 37108210, 2023). "Its precursor amino acid lysine on, the other hand, has been reported to be inversely associated with early metabolic syndrome and inflammatory markers, such as IL-6 and oxidised LDL, as well as GI." (PMID 37110149, 2023). "In fact, in a subgroup of patients with more severe asthma, a significant relationship with concomitant hyper-tension and metabolic syndrome has been revealed, the increase in interleukin-6 (IL-6) being the hallmark of this group of patients." (PMID 36983294, 2023). "The raised IL-6 level is often associated with dyslipidemia, evidenced by reduced HDL-C and increased TG levels in individuals with the inflammatory disease." (PMID 37764492, 2023). "Intriguingly, our study reports decreased levels of several pro-inflammatory cytokines in NASH that have been associated with the metabolic syndrome, such as IL-6 and IL-18." (PMID 37342340, 2023). "We have demonstrated that inflammatory cytokines such as TNF-α, IL-6, and IL-1β are soluble mediators linked with ventricular arrhythmias and contractile dysfunction in a rat model of metabolic syndrome." (PMID 37661270, 2023). "High IL-6 combined with low IL-10 levels were associated with risk of metabolic syndrome (OR 3.83, 95%CI 1.07–13.75, p = 0.039)." (PMID 35135482, 2022).
metabolic syndrome (continued). "Metabolic syndrome causes systemic chronic inflammation and an increase in IL-6, which are also associated with increased platelet production, and more risk factors for metabolic syndrome have been positively associated with a higher platelet count." (PMID 35453642, 2022). "In the genotyping of 578 individuals, we found significant association between PALMD and IL6 polymorphisms and aortic stenosis in patients with tricuspid aortic valve, independently of other potentially confounding variables such as age and dyslipidemia." (PMID 36337884, 2022). "TNF-α and IL-6 are implicated in dyslipidemia through the secretion of NEFA from visceral fat lipolysis." (PMID 35887592, 2022). "Metabolic syndrome was associated with the elevation of type 1 T helper cells in conjunction with many cytokines, including IL-6 and TNF." (PMID 36431254, 2022). "NAFLD is closely associated with metabolic syndrome and immunologically activated adipose tissue, a major site of IL-6 production." (PMID 35743825, 2022). "Overall, replacing processed foods with high nutrients products reduced the risk of dyslipidemia and the risk of changes in both IL-6 and IL-8 by less important changes in body mass." (PMID 34070364, 2021). "In metabolic syndrome (MS), chronic inflammation is caused by the primary secretion of fat cells of TNFα, and IL6." (PMID 33429991, 2021). "Within non-European background, in Chinese population, NR3C1 rs770144345 was significantly associated with a higher risk of metabolic syndrome and CC alleles of IL-6 rs152410746 had a higher risk of developing nephropathy in T2DM subjects." (PMID 33542408, 2021). "The increased levels of proinflammatory cytokines (TNF-α, IL-6, and IL-1β) have been found to be important contributors to the underlying processes of the development of metabolic syndrome." (PMID 30863477, 2019). "The plasma level of IL-6 is almost exclusively determined by whole-body adiposity and thus closely associated with metabolic syndrome." (PMID 30697360, 2019). "Although the association between IL6 and cellular proliferation is known, to our knowledge this is the first study to demonstrate that this association occurs independently of dyslipidemia in a patient-based study." (PMID 30631282, 2018). "Inflammatory cytokines, including IL-6 and TNFα, which affect skeletal muscle, the vasculature, and other tissues, cause pathologies associated with frailty and the metabolic syndrome." (PMID 29559978, 2018). "Not surprisingly, a great number of experimental and clinical studies have shown that metabolic syndrome is directly associated with circulating IL-6, TNF-α, and CRP, and that it is inversely correlated with IL-10 levels." (PMID 30558209, 2018). "Polymorphisms in IL-6 and serum levels of IL-6 have been shown to be associated with an increased risk of metabolic syndrome." (PMID 27287704, 2016). "We investigated IL-1, IL-6 and TNFα production and toll-like receptor 4 in both—obese and lean patients with non-alcoholic fatty liver disease who met different sets of metabolic syndrome criteria and linked the results with the disease burden." (PMID 26629827, 2015). "Visceral adipose tissue secretes inflammatory cytokines such as interleukin-6 and tumor necrosis factor α, which are associated with both obesity-related glomerulopathy and metabolic syndrome." (PMID 24533159, 2014). "The traditional risk factors for CHD, such as age, dyslipidemia, waist circumference and RI values were associated with IL-1, IL-6 and TNF-α." (PMID 25329057, 2014). "It is well acknowledged that IL-6 has been implicated in cardiovascular atherosclerotic risk, dyslipidemia, and hypertension." (PMID 21547256, 2011). "Increased circulating IL-6 is associated with a number of cardiac risk factors, including atherosclerotic disease, cardiomyopathies, and metabolic syndromes." (PMID 19936194, 2008).
metabolic syndrome (continued). "In obese women with metabolic syndrome, authors identified a lower concentration of the anti‐inflammatory adiponectin, whereas in obese men, the presence of metabolic syndrome is associated with higher circulating leptin and IL‐6 concentrations and increased PBMC cytokine production capacity." (PMID 41489606, 2026). "Similarly, interleukin-6 (IL-6), a key regulator of inflammatory responses, has been associated with dyslipidemia and metabolic disorders." (PMID 40427653, 2025). "However, we observed significant differences in parameters related to carbohydrate and lipid metabolism—key components associated with the risk of metabolic syndrome—as well as in the concentrations of proinflammatory markers, including IL-1β, IL-6, and CRP." (PMID 40944273, 2025). "Specifically, we focused on TNF-α and IL-6, and a wider range could provide a more comprehensive understanding of the inflammatory mechanisms associated with metabolic syndrome." (PMID 40137151, 2025). "Zang Hanue Xu suggests that the increase in IL-6 levels is associated with dyslipidemia." (PMID 40699654, 2025). "In regards to lipid metabolism, IL-6 has been linked to the development of dyslipidemia and a massive mobilization of fatty acids that may lead to lipid accumulation in the myocardium, potentially causing cardiac lipotoxicity." (PMID 41141350, 2025). "Future risk models may nonetheless benefit from incorporating IL-6, particularly in patients with metabolic syndrome, CAD, or residual inflammatory risk despite standard therapies." (PMID 40806466, 2025). "Specifically, inflammatory factors, such as TNF-α and IL-6, are associated with dyslipidemia." (PMID 38802874, 2024). "According to the hypothesis that inflammation causes dyslipidemia in RA patients, the finding of this study can disclose the possible impact of IL‐6, as an important inflammatory agent, in dyslipidemia and increase the risk of CVD in RA patients." (PMID 39160453, 2024). "A previous study in the NESDA cohort adopting a similar approach showed that the AES profile was specifically associated with an inflammatory index (integrating CRP and IL-6 levels), a metabolic syndrome index (integrating the five metabolic syndrome components) and their combination." (PMID 37301859, 2023). "Besides, emerging evidence has suggested that there are sex differences in the associations between IL-6 levels and various illnesses, including chronic hepatitis C, metabolic syndrome, etc.; however, there is limited study on TRS." (PMID 37370004, 2023). "Similarly, an elevated IL-6 level, and associated enhancement of TG and LDL-C levels were observed in individuals with psoriatic arthritis than psoriasis alone, signifying IL-6 was associated with dyslipidemia with autoimmune disease patients." (PMID 37764492, 2023). "However, in men, metabolic syndrome is associated with increased monocyte-derived circulating cytokines (mainly IL-6) and hyperresponsive circulating immune cells." (PMID 36419769, 2022). "A high IL-6 combined with a low IL-10 was associated with an increased risk of metabolic syndrome." (PMID 35135482, 2022). "As a result, it was hypothesized that SLE might cause dyslipidemia by decreasing the levels of resolvin D1 to increase the levels of inflammatory biomarkers such as IL-6 and CRP." (PMID 36120439, 2022). "Accordingly, we previously showed that ex vivo treatment for 2 h with H2O2 (produced with glucose oxidase) in PBMCs from patients with metabolic syndrome to mimic chronic stress caused a transient inflammatory response with an increase in the production of IL6, IL8, and IL1β." (PMID 34065281, 2021). "Given that tocilizumab is an IL-6 inhibitor which blocks the IL-6 receptor, it was found that IL-6 levels appear to be increased after treatment, which suggests that the mechanism underlying dyslipidemia is due to the direct effect of IL-6." (PMID 34422057, 2021).